ENSG00000221148
Synonyms: LOC124900326
Gene: Small nucleolar RNA gene on chromosome 12 (84,183,324 to 84,183,448, reverse strand). Ensembl gene ENSG00000221148.
Gene Ontology:
Biological process: RNA processing
Cellular component: nucleolus
Homologues: Paralogues in human: SNORA3B (83% identical), SNORA3C (73% identical), SNORA3A (61% identical).